CACNA1A (calcium voltage-gated channel subunit alpha1 A)
Diseases named in the same sentence as CACNA1A in open-access papers (continued):
Sharing a sentence is not in itself a finding about the gene and the disease.
peripheral neuropathy (2 papers, 2014 to 2019). A disorder affecting the peripheral nervous system. "The variants CACNA1A c.6692G > A (NM_023035.2), BAG3 c.494C > T (NM_004281.3), and ITPR1 c.6692A > G (NM_001168272.1) did not segregate with the peripheral neuropathy phenotype." (PMID 31852952, 2019).
vascular disorder (2 papers, 2023 to 2025). A general term used to describe any disease affecting blood vessels]. "In their ultrastructural study conducted on CACNA1A variant FHM1 patients, Dziewulska and Kierdaszuk observed microvascular changes, suggesting that the disease is not only functional but also a structural vascular disorder." (PMID 40111503, 2025).
adenocarcinoma (1 paper, 2010). A common cancer characterized by the presence of malignant glandular cells. "Among the novel methylated candidates identified, ID4, BNIP3, H2AFX, CACNA 1G, TGIF were more frequently methylated in squamous tumors, while HTLF and CACNA1A were commonly methylated in adenocarcinomas." (PMID 20849603, 2010).
autosomal dominant disease (1 paper, 2022). Autosomal dominant form of disease. "This autosomal dominant disease is caused by the expansion of a CAG repeat tract in the CACNA1A gene that encodes the α1A subunit of the P/Q type voltage-gated Ca2+ channel." (PMID 36078147, 2022).
CACNA1A also shares sentences with these, for which no sentence is quoted: cerebellar ataxia (42 papers); Huntington disease (22); migraine with aura (13); infection (12); Atrophy (11); cerebellar degeneration (7); familial hemiplegic migraine-1 (7); Alzheimer disease (6); autosomal dominant cerebellar ataxia (6); multiple system atrophy (6); spinocerebellar ataxia type 1 (6); amyotrophic lateral sclerosis (5); ataxia telangiectasia (5); ischemia (4); Seizure (4); Adult onset (3); breast carcinoma (3); cognitive decline (3); depression (3); developmental and epileptic encephalopathy, 42 (3); Dravet syndrome (3); melanoma (3); mitochondrial disease (3); multiple system atrophy of cerebellar type (3); spastic ataxia (3); Angelman syndrome (2); autoimmune disease (2); autonomic dysfunction (2); behavior disorders (2); brain ischemia (2).
A further 157 diseases each share a sentence with CACNA1A in 2 papers or fewer.